VIM (vimentin)
Diseases named in the same sentence as VIM in open-access papers (continued):
Sharing a sentence is not in itself a finding about the gene and the disease.
tumor (continued). "In addition, decreased expression of vimentin, Twist, MMP-2 and MMP-9 is associated with inhibition of tumor growth, cell migration, invasion and cancer metastasis and increased sensitivity to chemotherapeutic agents." (PMID 38737746, 2024). "Positive vimentin may reflect a reversal to a more embryonic, dedifferentiated phenotype, lending to a tumor’s more aggressive nature." (PMID 39199675, 2024). "Increased expression of VEGF, PCNA, and vimentin was observed in the tumor tissue." (PMID 39029008, 2024). "STAS was correlated with lower E-cadherin and higher vimentin expression in NSCLC, indicating that STAS could be associated with the epithelial–mesenchymal transition, a biological process that promotes tumour cell migration and invasion." (PMID 39705189, 2024). "We could confirm the expected expression of Vimentin positivity by immune and stromal cells and its absence within tumor cells." (PMID 38424144, 2024). "This analysis revealed a loss of the immune-related molecule CCL2 over time, contributing to a “cold” tumor microenvironment, and an increase in metastasis-associated molecules like MITF, KIT, and VIM, suggesting a potential transition to a mesenchymal phenotype." (PMID 38975339, 2024). "Additionally, tumor tissues from patients with low SVM_score showed increased expression of Vimentin, signifying higher EMT activation pathway and an increased metastasis propensity." (PMID 38987529, 2024). "The expression of KRT7 correlates with the tumor growth and metastasis and the levels of the EMT-associated transcription factors (SNAI1, SNAI2, TWIST1, TWIST2), and the mesenchymal markers, such as fibronectin, and vimentin (VIM)." (PMID 39329988, 2024). "To get a clue on this vimentin-dependent survival benefit in suspended cells, we first analyzed a publicly-available single cell RNA sequencing experiment conducted on pancreatic circulating tumor cells (CTC)." (PMID 38915055, 2024). "Specifically, the restoration of Vimentin expression could fully reverse the tumor suppressive effect of NEURL3 overexpression in NPC cells." (PMID 38191501, 2024). "However, tumor cells often show positivity for vimentin, desmin, smooth muscle actin, CD34 or estrogen, and progesterone receptors." (PMID 39463662, 2024). "Similarly, 68% of EBV-positive tissues exhibited a strong (+ 3) vimentin staining intensity pattern in tumor stroma, compared to EBV-negative tissues." (PMID 38705879, 2024). "Additionally, IHC staining demonstrated LYRM2 knockdown resulted in an increased level of E‐cadherin, while decreasing the expression of N‐cadherin and vimentin in the tumour tissues." (PMID 39661026, 2024). "ANGPTL4 overexpression could promote OC cell growth (tumor weight and volume) with higher expression of vimentin, proliferating cell nuclear antigen (PCNA), MMP9, ESM1 and CD34, which could be rescued by AG490." (PMID 38212795, 2024). "Also, high vimentin expression has been correlated with tumour growth, invasion, motility, directional migration and increased cell stiffness in breast, prostate, lung and melanoma cancers." (PMID 38528037, 2024). "Immunohistochemically, the tumor cells showed positivity for vimentin, CD31, and ERG." (PMID 38667451, 2024). "A consequence of the activation of the EMT process in tumor cells is the acquisition of invasive and metastatic properties, due to the inhibition of E-cadherin expression and increased expression of mesenchymal markers such as vimentin and Twist." (PMID 38737746, 2024). "Targeted molecules can be transcription factors involved in EMT, such as Snail, Slug, and Twist, or EMT-related proteins, such as vimentin, N-cadherin, and others that may prevent tumor cells from metastasizing." (PMID 38398019, 2024). "Vimentin also affects tumor angiogenesis via the activation of the NOTCH signaling pathway." (PMID 38791431, 2024).
tumor (continued). "IHC results indicated that the protein levels of Ki-67 and vimentin were elevated in CAFs-miR-1290 mimics tumor tissues compared with CAFs-NC tumor tissues; while in CAFs-lv-OGN tumor tissues, Ki-67 and vimentin showed to be decreased compared with CAFs-NC tumor tissues." (PMID 38402185, 2024). "Notably, miR-210KOs reversed the expression levels of E-cadherin, Vimentin, and Snail.Previously, hypoxia was indicated to trigger tumor cells to undergoEMT." (PMID 39651070, 2024). "Indeed, Vimentin serves as a pro-oncogenic factor that negatively impacts the prognosis of various tumor types." (PMID 38191501, 2024). "Interestingly, there is evidence that isoflavonoids can reverse the EMT process by decreasing the expression of vimentin, Snail, and Twist and consequently reducing the invasiveness of tumor cells." (PMID 38737746, 2024). "Furthermore, the results of IHC staining of tumor sections showed that the expression of Ki-67 and vimentin in CD36−/− mice was much lower than that in C57BL/6J mice, while BAX expression was higher in CD36−/− mice." (PMID 38319449, 2024). "Interestingly, echinomycin-treated tumours showed dramatic reduction in SLUG and VIM protein relative to vehicle-treated tumours." (PMID 38238426, 2024). "Similar to the patients’ SARC tumor component and in contrast to the UroCa component, organoids were negative for additional epithelial markers (KRT5, KRT8), yet showed a strong expression of Vimentin, hallmark of mesenchymal-like cells." (PMID 37919480, 2023). "Group 1 tumor spheroids are highly enriched for programs associated the epithelial–mesenchymal transition, KRAS signaling, and Myc activity and express high levels of the metastasis markers, such as Vimentin, TWIST1, and ZEB2." (PMID 37728504, 2023). "Some tumor sections were immunostained with ready-to-use primary antibodies against broad-spectrum cytokeratin (CK), vimentin, calretinin, Wilms tumor gene-1 (WT-1), D2–40, Paird box 8, synaptophysin, chromogranin-A, inhibin-α, S-100, Melan-A, HMB45, CD34, and Ki-67 (Maixin, Fuzhou, China)." (PMID 38115250, 2023). "Furthermore, western blot detected several apoptosis-related proteins (Bax and Bcl-2), EMT pathway biomarkers related to tumor transition (E-cadherin and Vimentin) and cell cycle protein (CyclinD1)." (PMID 36854894, 2023). "In fact, considering the high degree of vimentin protein expression in primary ES cells and the direct Pearson correlation between CAII and vimentin, we suggest that ES cells may rely on vimentin for adhesion and tumor proliferation." (PMID 37958399, 2023). "The ability of tumor cells to escape from neoplasia in situ tissue, infiltrate lymphatic or blood vessels, and spread to distant sites is assisted by the upregulation of Vimentin expression, which gives tumor cells the shape and properties of mesenchymal cells." (PMID 37718450, 2023). "Among them, EMT is particularly important for tumor metastasis and migration because it can reduce the expression of cell adhesion molecules, convert the keratin cytoskeleton into vimentin, and enable cells to acquire some of the characteristics of mesenchymal stem cells." (PMID 35848121, 2023). "The NLRP11/KAT7/vimentin‐K104Ac pathway may be a crucial in the inflammation‐mediated EMT in tumor cells." (PMID 37424170, 2023). "One mouse with remission showed shrinkage in the palpable tumor after necropsy, and pan-cytokeratin (reactivity with 1, 2, 5, 6, 7, 8, 10, 11, 14,17, 18 and 19 cytokeratins) and vimentin IHC staining verified the presence of carcinoma, which was under the control of the immune system." (PMID 37515069, 2023). "Tumor cells that undergo EMT acquire spindle-shaped morphology (fibroblast-like), showing significant loss of cell–cell contact and an increased expression of mesenchymal markers such as vimentin." (PMID 37109048, 2023).
tumor (continued). "High coexpression of CD44, CD90 and vimentin and spindle shaped morphology, in combination with loss of EpCAM and retention of E-cadherin indicates partial EMT (pEMT) typical of aggressive tumor cells." (PMID 37063842, 2023). "In addition, other CAFs markers (vimentin and podoplanin) were also introduced to verify the status of CAFs in tumor of KPC mice." (PMID 36727832, 2023). "IHC staining demonstrated low p57 or E-cadherin and high vimentin levels in xenograft tumours derived from PLC/PRF/5-DAGLA cells but high p57 or E-cadherin and low vimentin levels in xenograft tumours from Hep3B-DAGLA-KD cells compared with the control tumours." (PMID 37414748, 2023). "In addition, we were able to identify different populations of tumor capsule overexpressing cancer-associated fibroblasts (CAFs) markers such as FAP, VIM, and ACTA2 as well as hepatic stellate cells markers (HGF, LRAT, RGS5)." (PMID 37932266, 2023). "Notably, PARK7+Mac−C2 and VIM+Mac−C1 exhibited a preference for expressing genes that were upregulated in M1 macrophages, suggesting their enhanced M1-like anti-tumor functions." (PMID 38095634, 2023). "Therefore, by performing vimentin IHC in tumour tissues from the animal model we corroborated the MS results." (PMID 37344532, 2023). "These resultssuggested that the increased vimentin expression in varying levelsin combination with decreased NKX3.1 expression could be an importantfactor augmenting aggressive tumor formation." (PMID 37720744, 2023). "Interestingly, CDH1 expression was lower and VIM expression was higher in the tumor samples with high CYSLTR1 expression, although the statistical significance was not achieved, possibly due to the smaller number of patients." (PMID 36834820, 2023). "However, there was a positive correlation between tumor size and vimentin expression (p = 0.029; Rho = 0.563)." (PMID 36833374, 2023). "During the EMT at the molecular level, tumor cells switch their epithelial markers, including epithelial cadherin (E-cadherin), zona occludens-1 (ZO-1), and claudin into mesenchymal markers, such as neural cadherin (N-cadherin) fibronectin and vimentin." (PMID 37367670, 2023). "Therefore, the cell-autonomous ability of vimentin-expressing cells to metastasize was assessed using an allograft tumor model." (PMID 37161053, 2023). "Because tumor migration is tightly associated with epithelial-to-mesenchymal transition (EMT), we further measured the expression levels of key EMT markers vimentin (VIM) and e-cadherin (E-CAD) and mediators (SNAIL and SLUG)." (PMID 38096163, 2023). "The tumour typically demonstrates the CK7-/CD117-/CK20+/vimentin+ immunophenotype." (PMID 36816543, 2023). "Next, we compared the ‘epithelial’ glandular YFP + EpCAM+ and solid YFP + EpCAM- organoid sublines, which showed increased EpCAM expression in the primary tumor glandular organoids and increased vimentin expression in the solid organoids, consistent with their partial EMT phenotypes." (PMID 36828915, 2023). "Vimentin was positive in 16 cases (59.3%) in the neoplasia cohort." (PMID 37787719, 2023). "However, the signals for pSrc, pSTAT3, 4-HNE, and vimentin were more abundant at the tumor boundary." (PMID 36446524, 2023). "Co-expression of Vimentin and Slug proteins induces a worse prognosis in neoplasms." (PMID 37528887, 2023). "Tumor cells in the CC, CA, and PC groups were positive for vimentin, on the basis of IHC staining." (PMID 36647790, 2023). "The rather inhomogeneous and punctual staining pattern for vimentin may be attributable to phagocytic tumor material from the tumor site." (PMID 37497409, 2023). "Tumor cells express mesothelial markers such as CK, calretinin, D2–40, WT-1, and vimentin." (PMID 38115250, 2023). "Furthermore, immunohistochemical staining was performed to detect E-Cadherin, Snail, and Vimentin in paraffin-embedded sections of nude mice tumor tissue sections." (PMID 37273536, 2023).
tumor (continued). "Then, neoplastic cells undergo EMT with increased VIM expression achieved through decreased promoter methylation in concert with active histone PTMs acquisition, enabling tumor growth and favoring local invasion and systemic dissemination, fostering disease progression." (PMID 36594099, 2023). "Vimentin positivity suggests that the tumor is derived from muscle fibroblasts." (PMID 37960784, 2023). "Tumor cells undergoing EMT exhibit molecular alterations, as demonstrated by the loss of epithelial marker E-cadherin, and the gain of mesenchymal markers, including N-cadherin and Vimentin." (PMID 37031183, 2023). "We next stratified 24 human primary OSCC specimens into 12 tumours that had evidence of lymph node metastasis or perineural spread, and 12 that remained metastasis free, and stained them for EpCAM, Vimentin and CD24." (PMID 37975646, 2023). "Additionally, SPRY4-IT1 can be used as a biomarker for the early diagnosis of NSCLC tumor cells with a poor prognosis because of epithelial–mesenchymal transition activation by regulating the E-cadherin and vimentin expressions." (PMID 37424727, 2023). "In addition, other CAFs markers (vimentin and podoplanin) were also introduced to verify the status of CAFs in tumor of xenograft models." (PMID 36727832, 2023). "In addition, the results of an immunohistochemical study of NSL11 tumour showed that cetuximab or talazoparib resulted in a significant increase in the expression of VIM and a significant decrease in the expression of CDH1." (PMID 37441599, 2023). "At this step, animals were euthanized, and tumor cells were stained with anti-human vimentin." (PMID 36319818, 2023). "Similarly, it was reported that cells at the tumor margin partially acquire mesenchymal effector proteins (e.g., vimentin) whilst maintaining cell–cell contacts, phenotypic of epithelial cells." (PMID 37175467, 2023). "The patients with clinical risk factors or higher vimentin expression in tumor tissues had lower rates of recurrence-free survival than did those without clinical risk factors or with low tumor vimentin expression." (PMID 36737832, 2023). "Additionally, we studied the expression of key proteins involved in the EMT process, including E-cadherin and vimentin, and of proteins related to the tumor phenotype, such as ER, PR, ERBB2, Ki-67, cytokeratin (CK) 8/18, CK5/6, CK14, and CD44." (PMID 36899736, 2023). "Furthermore, we validated our findings using highly relevant CRC clinical samples and investigated the clinical data to determine the relationship between the number of PGCCs, percentage of vimentin nuclear positivity, and degree of tumor differentiation." (PMID 37833712, 2023). "Furthermore, FAM171B exerts a stabilizing effect by interacting with vimentin and enhancing its stability, leading to the tumor progression." (PMID 37915048, 2023). "In addition, we performed qRT-PCR in vitro validation and found that APLP2,CDCA4 and VIM genes were significantly overexpressed in tumor tissues, and the expression of PTMA gene was also upregul XCated, but the difference lacked statistical significance." (PMID 38098487, 2023). "Moreover, the in vivo study verified that M871 clearly decreased the expression of N‐cadherin and Vimentin while increasing E‐cadherin expression in tumor tissues." (PMID 36039037, 2023). "Thus, the average proportion of vimentin-positive cells increased by 16.6 ± 5.4% in 13 patients with partial tumor regression and by only 10.3 ± 3.0% in 22 patients with complete regression (p = 0.16)." (PMID 36834676, 2023). "On the other hand, immunohistochemical staining showed that the expression of tumor progression markers such as N-cadherin, Vimentin, VEGF, Ki67, and Cyclin D1 was decreased along with the downregulation of VIRMA, except E-cadherin exhibited a contrary tendency." (PMID 36691046, 2023).
tumor (continued). "Ten tumors had not only heterogeneous morphologies but also a broad immunohistochemical profile: the tumor cells consistently moderately to strongly expressed Melan-A, Vimentin and TFEB; however, they showed only weak–moderate positivity for HMB45, AE1/AE3, P504s and CD10." (PMID 36830782, 2023). "Consequently, elevated VIM expression is considered one of the hallmarks of tumor development and prognosis." (PMID 38098487, 2023). "Indeed, it has been reported that in tumor epithelial cells, vimentin modulates keratin expression by switching from a differentiated to a dedifferentiated phenotype." (PMID 38139209, 2023). "Immunohistochemically, the tumor cells were positive for Vimentin, S-100, CD34 and MDM2." (PMID 37670330, 2023). "PAK also downregulated the expression level of Vimentin (an EMT marker) within the tumor tissue." (PMID 38082285, 2023). "Vimentin over-expression increases tumor growth, invasion, and poor prognosis in cancer." (PMID 37325423, 2023). "Immunohistochemical staining of E‐cadherin and Vimentin showed less Vimentin expression and more E‐cadherin expression in soft group than in stiff group, indicating that reduced matrix stiffness can inhibit tumor EMT in vivo." (PMID 36684109, 2023). "In pathological sections, we found VIM was expressed in some macrophages, with tumor cell nearby." (PMID 38095634, 2023). "Moreover, SYT1 overexpression promoted the dephosphorylation of ERK1/2 and downregulated the expressions of Slug and Vimentin, two proteins tightly associated with EMT in tumor metastasis." (PMID 37958455, 2023). "Note that as such, vimentin expression often correlates with tumor aggressiveness." (PMID 36744297, 2023). "IHC staining verified a significant decrease in YY1, a significant decrease in vimentin expression and a significant increase in E-cadherin expression in tumor tissues of the HMSN-ISO@ProA-PD-L1 Ab treated group, indicating that HMSN-ISO@ProA-PD-L1 Ab played a role in inhibiting EMT of tumors." (PMID 37408047, 2023). "Notably, we detected high levels of TGF‐β, N‐Cadherin, and VIM proteins but low level of E‐Cadherin in the xenograft tumours of control group." (PMID 36651490, 2023). "Importantly, we found that EMT-related Vimentin showed low expression when both Neogenin and Merlin were highly expressed in tumor tissues from the CRC patient." (PMID 36746934, 2023). "More importantly, over‐expression of miR‐590 could decrease N‐cadherin and Vimentin protein levels but increase the E‐cadherin level, suggesting miR‐590 acts as a tumor suppressor that restrains the EMT process in ESCC." (PMID 35655441, 2023). "Likewise, vimentin supports the cell against compressive stress as experienced during tumor growth, promoting cell migration and invasion." (PMID 37051546, 2023). "While Vimentin is normally the specific marker of mesenchymal cells, and is not usually present in normal epithelial cells, its expression was identified in epithelial cells under in‐vitro culture or in tumour cells of epithelial origin." (PMID 36412036, 2022). "Further, it was also reported that curcumin strongly hindered tumor EMT through downregulating Nkd2-Wnt-CXCR4 signaling, then mediation of EMT-associated markers E-cadherin and vimentin expressions, resulting in a reduction of invasive and metastatic abilities in SW620 CRC cells." (PMID 35308223, 2022). "During EMT, tumor cells lose their polarity and cellular adherence, which are characterized by the reduction of epithelial marker E-cadherin, and obtain motility and invasiveness, which are characterized by mesenchymal markers N-cadherin and vimentin." (PMID 35645793, 2022). "During the EMT of tumor cells, the expression of different epithelial markers (e.g., E-cadherin and β-catenin) is reduced, whereas the expression of mesenchymal markers (like fibronectin and vimentin) is induced." (PMID 35800071, 2022).